CD24 (CD24 molecule)
Diseases named in the same sentence as CD24 in open-access papers (continued):
Sharing a sentence is not in itself a finding about the gene and the disease.
neuroblastoma (continued). "Because this condition precluded terminal differentiation, the neuroblastomas may very likely have retained the expression of CD24." (PMID 38214542, 2024). "In this study, we examined the autoimmune consequences of effective tumor vaccination on multiple organ systems and tested the impact of targeting the CD24-Siglec signaling pathway on both the vaccine therapy and autoimmune effects in the mouse neuroblastoma model." (PMID 37346042, 2023). "In order to determine the effect on tumor immunity, we tested two neuroblastoma mouse models in which CD24-Fc was administered either at the time of tumor vaccination or three days following the initial vaccination to determine if the timing of CD24 signaling altered immunity." (PMID 37346042, 2023). "Here, we tested the hypothesis that host cellular protein CD24 can modulate the antiviral state of human neuroblastoma cells in vitro and can determine the permissivity of these cells to infection with ZIKV and other distinct classes of RNA viruses." (PMID 36016357, 2022). "Our findings that CD24 expression in neuroblastoma cells represses intracellular antiviral pathways support the proposal that CD24 may represent a novel biomarker in cancer cells for susceptibility to oncolytic viruses." (PMID 36016357, 2022). "Indeed, receptors essential for ZIKV entry such as AXL and CD24 that are overexpressed in glioblastoma and neuroblastoma cancer cells, respectively, are also present on many other cell types." (PMID 35163212, 2022). "By identifying cell membrane-associated proteins present in Zika virus susceptible cell lines, but absent in SK-N-AS cells, we implicated CD24 as a factor required for Zika viral permissiveness in neuroblastoma cells." (PMID 30044847, 2018). "A neuroblastoma tissue array containing 27 cases of neuroblastoma (including primary isolates resected from the region of the adrenal glands, pelvic cavity, mediastinum, and retroperitoneum) was stained for CD24 expression and compared with mature peripheral nerve tissue." (PMID 38214542, 2024). "The systemic administration of CD24-Fc, is sufficient to suppress autoimmune responses in the heart, but appropriate timing of administration is critical in order to avoid suppression of the vaccine therapy effect as noted in this mouse neuroblastoma tumor model." (PMID 37346042, 2023). "In the current study we evaluated L-, P- and E-selectin binding to neuroblastoma cells and the expression of some of their known ligands, namely CD44, CD24 and P-selectin glycoprotein ligand-1 (PSGL-1)." (PMID 29156825, 2017). "This was exemplified with the known neural differentiation marker CD24 under live, fixed, and fixed-and-permeabilized conditions on SH-SY5Y neuroblastoma cells." (PMID 23826393, 2013). "SK-N-AS is a non-MYCN amplified metastatic neuroblastoma cell line that endogenously expresses minimal levels of CD24." (PMID 36016357, 2022). "Restoring CD24 (SK-N-AS) expression in a low-permissive neuroblastoma cell line restores ZIKV oncolytic activity, unlike the CD24-deficient cell line." (PMID 35163212, 2022). "CD24 protein was easily detected in all neuroblastoma cell lines screened, except SK-N-AS cells, in which no CD24 protein was detectable." (PMID 30044847, 2018). "In order to exclude that the myelocytic cluster, co-expressing CD24, which is also highly expressed in DTCs, and the mesenchymal marker CD29, might contain mesenchymal-type neuroblastoma cells, we performed interphase fluorescence in situ hybridization (iFISH) subsequent to MELC." (PMID 34503120, 2021). "Regardless, siRNA-mediated silencing of CD24 expression reduced expression of viral NS1 protein and prevented Zika virus-induced cell death in IMR-32 cells (data not shown), indicating that CD24 is involved in the increased replication of Zika virus in IMR-32 neuroblastoma cells." (PMID 30044847, 2018).
neuroblastoma (continued). "Our prior work showed that differential infectivity across a range of neuroblastoma cell lines to ZIKV infection did not correlate with AXL expression, and our transcriptional data here indicate that CD24-low and -high cells do not differ in the levels of AXL expression." (PMID 36016357, 2022).
ovarian tumor (13 papers, 2013 to 2023). "CD24 is linked to an increased metastatic and invasiveness potential in ovarian tumors and a shortened patient survival and is associated with signaling factors, such as Src kinase in lipid rafts microdomains, and requires STAT3." (PMID 37189618, 2023). "By contrast, in patient-derived ovarian tumor samples, CD24-negative cells were more aggressive than CD24-positive cells, with stemness features and resistance to carboplatin and paclitaxel." (PMID 30551640, 2018). "The discoveries for the presence of microRNAs, EpCAM, and CD24 in ovarian tumor-derived exosomes have provided promising alternatives to early detection." (PMID 24460816, 2014). "In addition, CD24+ cancer cell colonies isolated from ovarian tumors of a human patient showed heterogeneity in proliferation rate, cell cycle distribution, and expression profile of genes and proteins, and demonstrated stem cell properties." (PMID 24955581, 2014).
acute myeloid leukemia (12 papers, 2011 to 2025). Acute myeloid leukemia (AML) is a group of neoplasms arising from precursor cells committed to the myeloid cell-line differentiation. "Overexpression of CD24 has been described on a number of human tumor cells, including acute myeloid leukemia." (PMID 30405620, 2018). "CD44 targeting is used in the treatment of acute myeloid leukemia (AML), CD24 targeting is for the treatment of colon and pancreatic cancer and CD133 is targeted for the treatment of hepatocellular and gastric cancer." (PMID 25071581, 2014). "Flow cytometry on peripheral blood revealed a diagnosis of acute myeloid leukemia (AML) with the blast cells expressing CD11b, CD11c, CD15, CD13, CD24, CD33, CD34, CD117, CD123 and HLA-DR." (PMID 41300735, 2025). "In patients with acute myeloid leukemia (AML), Bregs are categorized as CD19+, CD24+, and CD38+, and the presence of these cells is correlated with poor prognosis." (PMID 35746487, 2022). "In a very recent study performed on acute myeloid leukemia (AML) patients, Bregs are defined as CD19+ CD24+ CD38+." (PMID 31086070, 2019). "Notably, a study has been performed on acute myeloid leukemia (AML) where B cells include a higher proportion of regulatory B cells and display surface markers CD19, CD24, and CD38." (PMID 31684152, 2019).
adenoma (12 papers, 2012 to 2024). A neoplasm arising from the epithelium. "In Egypt, a completed observational trial (NCT04907422) employed CD24-AuNC as a diagnostic marker for Carcinoma Ex Pleomorphic Adenoma of Salivary Glands, proposing CD24-AuNC as a sensitive and specific diagnostic tool." (PMID 38881902, 2024). "Immunofluorescence analysis confirmed a corresponding decrease in the Lgr5-GFP+ tumor cell area and Sox9+, Prox1+, and Cd24+ adenoma cells in the intestinal sections 18 days after Lef1 deletion." (PMID 34788095, 2021). "We demonstrate that anti-CD24 monoclonal antibodies recognize CD24 expressed in PBLs isolated from plasma and compare its levels in patients undergoing colonoscopy who have CR adenomas, adenocarcinomas, or normal colon." (PMID 26078485, 2015). "The CD24 test has a sensitivity of 84.2% (95% CI, 60.4–96.4%) for the detection of advanced adenomas with a specificity of 73.5% (95% CI, 61.4–83.5%)." (PMID 26078485, 2015). "Western blot analysis showed high level of CD24 expression in PBLs obtained from individuals with adenomas and adenocarcinomas compared to those with normal colonoscopies." (PMID 26078485, 2015). "Within the adenoma patients in the second cohort, 4 out of 37 (10.8%) patients carried both SNPs and all four exhibited significantly lower level of CD24 protein." (PMID 26078485, 2015). "Indeed, when compared to the mucosa of wild-type gp130+/+ mice, we detected increased proportions of DCLK1+ and SiglecF+CD24+EpCAM+ tuft cells in the adenomas of gp130F/F mice, which coincided with an increased abundance of iILC2s, but not nILC2s." (PMID 37898600, 2023). "However, the tumor cells in Cd24−/− adenoma were considerably more advanced in malignant transformation based on the nuclei/plasma ratio and by the pleomorphic nuclei and the presence of mitotic tumor cells." (PMID 29423273, 2018). "In the MMTV-PyMT model we observed that hyperplastic pre-neoplastic lesions and small adenomas stained strongly for CD24, reflecting expression in the normal mammary epithelium, where it is predominantly present in the luminal epithelium and only weakly expressed in basal myoepithelial cells." (PMID 26978528, 2016). "The sensitivity and specificity of CD24 for distinguishing adenomas from normal subjects in our first trial were 84.2% (95% CI, 60.4–96.4%) and 73.5% (95% CI, 61.4–83.5%), respectively, whereas in the second trial a higher sensitivity of 89.2% (95% CI, 74.6–97%) was achieved for adenomas." (PMID 26078485, 2015). "The sensitivity and specificity of CD24 for distinguishing CRC from normal subjects were 70.5% (95% CI, 54.8–83.2%) and 83.8% (95% CI, 74.6–92.7%) and for adenomas 84.2% (95% CI, 60.4–96.4%) and 73.5% (95% CI, 61.4–83.5%), respectively." (PMID 26078485, 2015). "More recently, researchers in the Visvader laboratory have shown that, in cells derived from PyMT adenomas (early-stage lesions), CD14 and c-kit, along with CD49f/CD24, enriches for cells with colony-forming potential." (PMID 22225988, 2012). "Univariate analyses revealed that CD24 levels above the cutoff were independent of the subject's gender, age, size of adenoma, or stage of CRC (data not shown)." (PMID 26078485, 2015). "Thus, it seems that the sensitivity of CD24 versus FIT is comparable in detecting cancer; however, it is much more sensitive than FIT for adenoma detection." (PMID 26078485, 2015). "The sensitivity and specificity of the CD24 test for distinguishing adenomas and CRC from subjects without findings on colonoscopy in this study were relatively high as compared to other available screening tests." (PMID 26078485, 2015). "The positive predictive value (PPV) and negative predictive value (NPV) of CD24 for the detection of adenomas were 47.1% and 84.3%, respectively, versus 75.6% (PPV) and 81.7% (NPV) for CRC detection." (PMID 26078485, 2015). "Of note, some well-established carcinoma markers, including CD24, CD133, and EpCAM, were not upregulated in adenoma as compared to mucosa." (PMID 37667332, 2023).
adenoma (continued). "In determining the specificity and sensitivity of the CD24 test and its ability to discriminate between patients with CRC or adenoma from individuals without endoscopic findings, cutoff values for the detection of adenomas and CRC were derived." (PMID 26078485, 2015). "The specificity of CD24 for distinguishing between normal and CRC was lower at 65.0% (versus 83.8%) but comparable for adenoma, 76.7% versus 73.5% (data not shown)." (PMID 26078485, 2015).
Autoimmunity (12 papers, 2015 to 2025). The occurrence of an immune reaction against the organism's own cells or tissues. "Soluble CD24 (CD24Fc), which is linked to the Fc domain of human IgG1, was developed to treat inflammation associated with viral infections, autoimmunity, and graft-versus-host diseases." (PMID 41162542, 2025). "Even more, numerical and/or functional impairments in CD24+CD38+ or CD24+CD27+ Bregs were also implicated in autoimmunity (rheumatoid arthritis, psoriasis, systemic sclerosis), viral infection (hepatitis B virus), and allergy (allergic rhinitis)." (PMID 36685568, 2022). "CD24 is highly expressed by immune cells and cancer cells and it is known to play an inhibitory role in B-cell activation responses and the control of autoimmunity." (PMID 37207201, 2023). "Taken together, these data demonstrate that autoimmunity occurs to a different extent in various organ systems and the administration of CD24-Fc alleviates much of the autoimmune response observed." (PMID 37346042, 2023). "Another female-biased gene detected here, CD24, has a crucial role in T cell homeostasis and autoimmunity." (PMID 31615477, 2019). "One of the other largest effects of TYK2:p.Pro1104Ala mutation on immune cell levels was an increase in the absolute count of B cells, most notably the IgD+CD24− mature naïve B cells population increased, confirming the protective effect of naïve cells on autoimmunity." (PMID 39835539, 2025). "The role of CD24 in autoimmunity has not been clearly delineated." (PMID 25830931, 2015).
chordoma (12 papers, 2010 to 2024). Chordomas are rare malignant tumors arising from embryonic remnants of the notochord in axial skeleton. "Another promising approach involves the cell-surface protein CD24, which is frequently expressed in chordomas and – along with brachyury and low molecular weight cytokeratins – has been used as a diagnostic marker for chordoma in some cases." (PMID 36387127, 2022). "While EMA was strongly expressed by the three chordoma spheroid models, Brachyury and CD24 were highly expressed by the CH22 and U-CH1 spheroids and the U-CH12 spheroids displayed a low expression level." (PMID 33672032, 2021). "At the histological level, all three spheroid models expressed the chordomas markers Brachyury, CD24, cytokeratins, and EMA." (PMID 33672032, 2021). "Using the Affymetrix Human Genome U133 set GeneChip set, CD24 was highly expressed in chordoma (signal: 1409) compared to vertebral disc (p<0.00024; signal: 10) or to U-CS2 (signal: 62.9)." (PMID 24452533, 2014). "Our findings are consistent with recent molecular profiling of chordoma cells that identified CD24 in a list of potential candidates for chordoma tumorigenesis." (PMID 25541962, 2014). "Further investigations are needed in order to study the prognostic relevance of CD24 protein expression in chordoma." (PMID 24452533, 2014). "We demonstrate the expression of new potential candidates for chordoma tumorigenesis, such as CD24, ECRG4, RARRES2, IGFBP2, RAP1, HAI2, RAB38, osteopontin, GalNAc-T3, VAMP8 and others." (PMID 24452533, 2014). "The protein products of two of these genes, T (Brachyury) and CD24 (HSA, heat stable antigen), are used as diagnostic markers of chordoma and were therefore measured using biochemical approaches." (PMID 21253487, 2010). "Genes marked on the volcano plot were either implicated earlier in chordoma biology (e.g. keratins—KRT8, KRT18, KRT19, TBXT, LMX1A, and EGFR) or identified by outstanding p-value (e.g. IL11, CD24), high absolute fold-change (e.g. GABRA1) or DMR result (e.g. MNX1)." (PMID 37434245, 2023). "Intriguingly, tumor-derived CD24 was recently identified as a key anti-phagocytic “don’t eat me” signal in other solid tumors, making it a promising immunotherapeutic target and prompting evaluation of CD24 blockade in chordoma." (PMID 36387127, 2022). "CD24, a glycosylphosphatidylinostitol-anchored cell surface protein that functions in differentiation and activation of granulocytes and B lymphocytes, has been reported to be expressed by NP cells of rat and human chordoma (a notochordal-derived tumor)." (PMID 24101443, 2014). "For cell lines that lack Brachyury but have abnormal genetics (like CM319), expression of one or more markers of chordoma including CD24, collagen type II alpha 1, keratin 19, and carbonic anhydrase 3 could offer evidence of chordoma-derived cells." (PMID 21253487, 2010). "In vivo, 18 resected chordoma samples were evaluated using multispectral immunofluorescence for CSCs, defined as cytokeratin positive chordoma cells that triple stained for CD15, CD24 and ALDH." (PMID 38741774, 2024). "Prior chordoma studies have demonstrated that CD15, CD24, CD133, and ALDH are markers for tumorigenic CSCs." (PMID 38741774, 2024). "Chordoma CSCs quantified from cell culture using a CD24+CD133+ signature comprised <5% in all cell lines but one, whereas CSCs appraised within imaged chordoma tumor samples using the CD15+CD24+ALDH+ signature comprised 1.39% of tumor cells." (PMID 38741774, 2024). "We investigated the relative expression levels (mean fluorescence intensity; MFI) of CD24, CD133, CD15, and ALDH in the CD24high/CD133high group in 4 chordoma cell lines." (PMID 27172898, 2016). "Prior chordoma studies have illustrated that CSCs may be defined by surface expression of various combinations of markers, including CD15, CD24, CD133, and ALDH." (PMID 38741774, 2024).
chordoma (continued). "Our data suggest that, as the stem markers, CD24, CD133, CD15, and ALDH could identify a residential CSC subpopulation in chordoma." (PMID 27172898, 2016). "With respect to immunohistochemistry and FACS analysis, it was demonstrated that CD24 antigen is highly abundant in all chordomas, but is absent in conventional skeletal chondrosarcomas." (PMID 24452533, 2014). "In our cohort of chordoma and chondrosarcoma, we demonstrated by immunohistochemistry and, in part, by FACS analysis that our chordoma cell lines and the fresh-frozen chordomas (n=7) express CD24 protein." (PMID 24452533, 2014). "A recent study showed that CD24 is expressed by rat NP cells of rat and human chordoma (notochodal tumor)." (PMID 23284858, 2012). "CM319 does not appear physaliferous and does not express most genes typically expressed by chordoma tumors; however, it has abnormal genetics consistent with being a cancer cell line and expresses CD24." (PMID 21253487, 2010). "Furthermore, CD24, which is not expressed in chondrosarcomas, is detected in the herniated NP and chordomas and is therefore considered a surface marker specifically expressed by NP cells." (PMID 35409417, 2022).
B-cell lymphoma (11 papers, 2015 to 2023). "Murine primary BM-derived B cells and a murine pre-B cell lymphoma cell line (WEHI-231) were shown to release CD24+ plasma membrane-derived sEV upon CD24 engagement." (PMID 37762077, 2023). "Here, we investigated this axis in B-cell lymphoma by assessing CD24 expression and evaluating pro-phagocytic effects of CD24 antibody treatment in comparison to hallmark immune checkpoint CD47." (PMID 35625912, 2022). "Despite CD24 being used as a differentiation marker of lymphocytes in the hematology field, only a few studies have reported on CD24 in mature B‐cell lymphoma related to its expression and clinical impact." (PMID 35289116, 2022). "CD24 is also reportedly expressed in various cancers, including non-Hodgkin B-cell lymphomas (NHLs) in which CD24 levels were elevated compared to healthy subjects." (PMID 35625912, 2022). "Future studies will be needed to determine if EV heterogeneity and CD24-mediated regulation of EV surface protein composition is generalizable to other B cell lymphomas, healthy B cells, or other CD24-expressing cells." (PMID 28819186, 2017). "Furthermore, CD24 or B cell receptor (BCR) stimulation on a B cell lymphoma cell line triggered the secretion of sEV that carried functional BCR and CD24 to recipient B cells." (PMID 37762077, 2023). "This would be in line with macrophage-dependent ADCP as reported in the initial clinical trial of combination treatment with murine CD24 and CD21 mAbs of B-cell lymphoma patients." (PMID 35625912, 2022). "The implication of MYC rearrangement in CD24‐expressed lymphoma prompted us to explore the relationship between MYC aberration and CD24 expression in B‐cell lymphoma including Burkitt lymphoma (BL)." (PMID 35289116, 2022). "In this study, we investigated the role of CD24 as a therapeutic target preclinically using cell lines and primary patient-derived samples, with a particular focus on MCL and DLBCL, but also other B-cell lymphomas such as follicular lymphoma and Burkitt lymphoma." (PMID 35625912, 2022). "If MYC regulates CD24 expression directly, CD24 may be one of the surrogate markers of mature B‐cell lymphoma with MYC aberrations including HGBL and ‘double expressor’ B‐cell lymphoma." (PMID 35289116, 2022).